SLC10A2 (solute carrier family 10 member 2)
Description:
Plays a critical role in the sodium-dependent reabsorption of bile acids from the lumen of the small intestine. Transports various bile acids, unconjugated or conjugated, such as cholate and taurocholate. Also responsible for bile acid transport in the renal proximal tubules, a salvage mechanism that helps conserve bile acids (Probable). Works collaboratively with the Na(+)-taurocholate cotransporting polypeptide (NTCP), the organic solute transporter (OST), and the bile salt export pump (BSEP), to ensure efficacious biological recycling of bile acids during enterohepatic circulation.
Synonyms: ASBT; IBAT; ISBT; NTCP2; PBAM; PBAM1
Tractability: Small molecule: an approved drug acts on it; a high-quality ligand is known; it belongs to a druggable protein family. Antibody: its Gene Ontology location is reachable by antibodies, with high confidence; UniProt predicts a signal peptide or a membrane-spanning region. PROTAC: a small molecule that binds it is known.
Target class: SLC superfamily of solute carriers; Electrochemical transporter; SLC10 family of sodium-bile acid co-transporters; Transporter
Safety:
Unwanted effects reported when the protein is acted on. In parentheses: how it was acted on, where the effect was seen, and who reports it.
cardiotoxicity (source: ClinPGx)
drug toxicity (source: ClinPGx)
Gene: Protein-coding gene on chromosome 13 (103,043,998 to 103,066,417, reverse strand). Ensembl gene ENSG00000125255.
Subcellular location: Membrane
Pathways (Reactome):
Metabolism: Recycling of bile acids and salts
Gene Ontology:
Molecular function: protein binding; bile acid:sodium symporter activity
Biological process: bile acid and bile salt transport
Cellular component: apical plasma membrane; plasma membrane; membrane; microvillus
Genetic constraint (gnomAD): Loss-of-function variants: 26 observed, 24.64 expected, observed/expected ratio (o/e) 1.06, 90% interval 0.77 to 1.46. The upper end of that interval is the gene's LOEUF score, 1.46, which puts it in group 6 of 6, group 1 being the genes least tolerant of losing a copy. Missense variants: 488 observed, 430.96 expected, observed/expected ratio (o/e) 1.13, 90% interval 1.05 to 1.22. Synonymous variants: 190 observed, 170.9 expected, observed/expected ratio (o/e) 1.11, 90% interval 0.99 to 1.25.
Homologues: Orthologues: chimpanzee SLC10A2 (99% identical), macaque SLC10A2 (96% identical), dog SLC10A2 (88% identical), rabbit SLC10A2 (86% identical), rat Slc10a2 (83% identical), pig SLC10A2 (81% identical), mouse Slc10a2 (80% identical), guinea pig SLC10A2 (77% identical), tropical clawed frog slc10a2 (69% identical), zebrafish slc10a2 (60% identical). Paralogues in human: SLC10A6 (45% identical), SLC10A1 (33% identical), SLC10A4 (33% identical), SLC10A5 (27% identical), SLC10A3 (22% identical).